RPL11 (ribosomal protein L11)
Diseases named in the same sentence as RPL11 in open-access papers (continued):
Sharing a sentence is not in itself a finding about the gene and the disease.
lung carcinoma (7 papers, 2015 to 2024). "uL5/RPL11 and uL18/RPL5 also contribute strongly to the maintenance of nucleolar structure in cell lines for colon cancer (HCT116) and lung cancer (A549 and H1944)." (PMID 37047306, 2023).
gastric cancer (6 papers, 2020 to 2025). A primary or metastatic malignant neoplasm involving the stomach. "In cervical cancer and gastric cancer, RPL11 contributed to tumorigenesis by translocating to the cytoplasm and further binding to MDM2." (PMID 36869281, 2023). "For example, RPS15A was found to promote the progression of gastric carcinoma by activating the Akt pathway, and RPL11 expression was identified as a potential biomarker for predicting 5-fluorouracil (5-FU) sensitivity." (PMID 35847905, 2022).
lung adenocarcinoma (6 papers, 2016 to 2023). A carcinoma that arises from the lung and is characterized by the presence of malignant glandular epithelial cells. "However, they showed no direct evidence of RPL11 in regulating the lung adenocarcinoma cells proliferation." (PMID 36869281, 2023).
colon cancer (5 papers, 2021 to 2023). "Further analysis revealed that some of these genes, notably rps15, rpl11, rpl18, and rpl36, are significantly increased in primary adenocarcinoma tissue samples and co-ordinately predict for worse overall survival of colon cancer patients." (PMID 37888706, 2023). "On the other hand, RPL11 and RPL18 proteins had moderate intensity in colon tissue, whereas RPS15 and RPL36 showed strong staining intensity in colon cancer tissue." (PMID 37888706, 2023). "We found that higher expression of RPS15, RPL11, RPL18 and RPL36 could individually predict worse overall survival (OS) of patients with colon cancer compared to the low expression of these genes." (PMID 37888706, 2023). "Finally, based on this evidence, we hypothesized that since these genes are implicated in similar pathways related to ribosomal biosynthesis and protein translation, RPS15, RPL11, RPL18 and RPL36 expression levels may coordinately predict the survival of patients with colon cancer." (PMID 37888706, 2023).
liver cancer (5 papers, 2021 to 2024). An epithelial or non-epithelial malignant neoplasm that arises from the liver. "In liver cancer, RPL11-mediated MID1 interacting protein 1 depletion reduced cell viability and colony formation by inhibiting MYC gene expression." (PMID 36869281, 2023). "Our previous studies show that MID1IP1 regulates liver cancer growth through c-Myc mediated by ribosomal protein L5 (RPL5) and L11 (RPL11)." (PMID 34680125, 2021).
osteosarcoma (5 papers, 2021 to 2022). A usually aggressive malignant bone-forming mesenchymal neoplasm, predominantly affecting adolescents and young adults. "New signatures of four pseudogenes, RP11-326A19.5, RP4-706A16.3, RPL7AP28, and RPL11-551L14.1, for osteosarcoma were found, which is a promising independent survival predictor and serves as an important biomarker for clinical treatment of osteosarcoma to improve patient management." (PMID 34947885, 2021). "RPL11, affecting osteosarcoma malignant phenotype, may be a new prognostic markers of osteosarcoma survival." (PMID 33305312, 2021).
T-cell acute lymphoblastic leukemia (4 papers, 2018 to 2023). Acute lymphoblastic leukemia of T-cell origin. "In fact, mutations in ribosomal protein-coding genes have been reported in the literature in relation to T-cell acute lymphoblastic leukemia (RPL5 and RPL11) and gliomas (RPL5)." (PMID 36865483, 2023).
anemia (3 papers, 2013 to 2024). A reduction in the number of red blood cells, the amount of hemoglobin, and/or the volume of packed red blood cells. "Demonstrating robust effects in vitro, these inhibitors also enhanced hematopoiesis and erythropoiesis in immunodeficient NPSG and NCG-X mice and various anemia models, including the Rpl11 haploinsufficiency mouse model of DBA." (PMID 39617757, 2024). "In vivo studies have shown that BRAFi can enhance human hematopoiesis and erythropoiesis in severe immunodeficient mouse models and alleviate anemia in the Rpl11 haploinsufficiency DBA model, as well as other relevant anemia models." (PMID 39617757, 2024). "The Rpl11 haploinsufficiency DBA mouse model, reported to recapitulate macrocytic anemia and erythroid marrow failure characteristic of the disorder, was validated in our studies." (PMID 39617757, 2024).
diabetes (3 papers, 2022 to 2025). "Furthermore, RPL11 exhibits sustained upregulation in multiple non-healing wound models, including those driven by aging (98-week-old mice), diabetes (db/db mice), and inflammation (LPS-induced wounds)." (PMID 40895534, 2025).
glioma (3 papers, 2018 to 2025). A benign or malignant brain and spinal cord tumor that arises from glial cells (astrocytes, oligodendrocytes, ependymal cells). "GNL2 enhances the synthesis of ribosomal protein L11 (RPL11), thereby promoting glioma development." (PMID 39949372, 2025).
acute lymphoblastic leukaemia (2 papers, 2018 to 2022). "Among 211 T cell–acute lymphoblastic leukaemia (T-ALL) patients, a subset (11 and 4, respectively) have mutations in RPL11 and RPL5." (PMID 35472285, 2022).
leukaemia (2 papers, 2022 to 2023). "Exome sequencing and other approaches have further shown that mutations in RPL5 (uL18), RPL10 (uL16), RPL11 (uL5), RPL22 (eL22), RPS15 (uS19) and RPS20 (uS10) are present in a variety of cancers, especially leukaemia." (PMID 37526268, 2023). "RPL11 mRNA expression in leukemia cells at relapse decreased in seven out of nine patients compared to that at diagnosis." (PMID 36291909, 2022). "We examined RPL11 mRNA expression in leukemia cells collected from the bone marrow of pediatric patients with BCP-ALL with relapse." (PMID 36291909, 2022). "In the present study, decreased expression of RPL11 drastically reduced sensitivity to 6-mercaptopurine and methotrexate in BCP-ALL cell lines and leukemia cells." (PMID 36291909, 2022).
non-small cell lung carcinoma (2 papers, 2023 to 2025). A group of at least three distinct histological types of lung cancer, including non-small cell squamous cell carcinoma, adenocarcinoma, and large cell carcinoma. "Here, we aimed to unravel the role of RPL11 in non-small cell lung cancer (NSCLC), especially those affecting cell proliferation." (PMID 36869281, 2023). "Illustrating this view, RPL11 is more highly expressed in non-small cell lung carcinoma (NSCLC) cell lines compared to non-tumorigenic HBE cells." (PMID 40940922, 2025).
ovarian carcinoma (2 papers, 2023 to 2025). A malignant neoplasm originating from the surface ovarian epithelium. "RPL11 has the potential to be used as a biomarker in ovarian cancer due to its expression level and functional involvement in tumor biology." (PMID 39891297, 2025). "Several hub genes, such as RPL11, RPS4X, EIF3I, and RPS14, have been previously linked to various cancers and were confirmed to play crucial roles in ovarian cancer through this study." (PMID 39891297, 2025). "We also found that apoptosis-related genes, URI1, PAK2, PARP1, CLU and TIMP3, were highly expressed, while immune-related genes, UBB, RPL11, CAV1, NUPR1 and Hsp90ab1, were lowly expressed in ovarian cancer cells." (PMID 37124501, 2023). "RT-qPCR analysis revealed that URI1, PAK2, PARP1, CLU, and TIMP3 were significantly upregulated, while UBB, RPL11, CAV1, NUPR1, and Hsp90ab1 were significantly downregulated in the ovarian cancer samples." (PMID 37124501, 2023).
prostate carcinoma (2 papers, 2010 to 2011). A carcinoma that arises from epithelial cells of the prostate gland. "Moreover, unlike the situation in Myc-induced lymphomagenesis in which ribosomal protein L11 expression was significantly increased, L11 expression was not induced by APT121 (data not shown), suggesting that APT121-induced prostate cancer does not cause ribosomal stress." (PMID 21747916, 2011).
Sepsis (2 papers, 2021). Sepsis is defined as life-threatening organ dysfunction caused by a dysregulated host response to infection. "We performed feature selection analysis and found that combination of three genes (TLCD4, PRSS30P, and ZNF493) and seven genes (TLCD4, PRSS30P, ZNF493, AGO2, SLC37A3, SLC2A1, and RPL11) showed moderate performance in identifying patients with sepsis and ARDS within 1 day after admission." (PMID 33818300, 2021). "In particular, the qPCR analysis showed significant down-regulation of RPL11, RPS21, NCBP2, and MRRF during sepsis." (PMID 34594344, 2021). "The transcription levels of RPL11 (ribosomal protein L11), RPS21 (ribosomal protein S21), NCBP2 (nuclear cap binding protein subunit 2), and MRRF (mitochondrial ribosome recycling factor) were found to be significantly reduced in the sepsis group as compared to the control group (p‐value < 0.05)." (PMID 34594344, 2021).
Alzheimer disease (1 paper, 2021). A progressive, neurodegenerative disease characterized by loss of function and death of nerve cells in several areas of the brain leading to loss of cognitive function such as memory and language. "RPL11 is a ribosomal protein, and previous sequencing experiment analysis studies on amyotrophic lateral sclerosis, Alzheimer’s disease, and dementia human subject samples showed remarkable alterations in the RPL11 protein." (PMID 34827437, 2021).
brain arteriovenous malformations (1 paper, 2023). "Commonly associated with retinal degeneration, the RPL11 gene has also been associated with brain arteriovenous malformations and cancer in humans." (PMID 38132326, 2023).
campomelic dysplasia (1 paper, 2021). "In this respect, it is tempting to speculate on the classification of campomelic dysplasia (OMIM #114290), as links between Sox9 and genes involved in ribosomopathies were identified in the present work (SBDS, Rpl11, and Rps26)." (PMID 34235151, 2021).
glioblastoma (1 paper, 2013). The most malignant astrocytic tumor (WHO grade IV).
Hyperglycemia (1 paper, 2022). An increased concentration of glucose in the blood. "It has not been studied in the case of DM, but we can hypothesize that DM provokes disturbances in ribosome biogenesis, as a consequence of hyperglycemia, inducing ASCs stress which in turn produces an accumulation of free fractions of RPL11, and their increased susceptibility to undergo apoptosis." (PMID 35655589, 2022).
Macrocephaly (1 paper, 2022). Occipitofrontal (head) circumference greater than 97th centile compared to appropriate, age matched, sex-matched normal standards. "Considering that RPL11 is the only affected gene in the deleted segment, further genetic analysis would be needed to ensure if this is the only pathogenic variant carried by this patient and establish if this variant is indeed the cause of macrocephaly." (PMID 36553552, 2022).
malignant rhabdoid tumors (1 paper, 2022). "In the present study, using rhabdomyosarcoma and rhabdoid tumor cell lines that are sensitive to the nucleolar stress response, we investigated the effect of RPL11-mediated nucleolar stress response on sensitivity to topoisomerase inhibitors." (PMID 36555627, 2022).
neuroblastoma (1 paper, 2016). Neuroblastoma (NB) is the most common solid, extracranial childhood tumor.
Obesity (1 paper, 2018). Accumulation of substantial excess body fat.
cancer (55 papers, 2010 to 2025). A tumor composed of atypical neoplastic, often pleomorphic cells that invade other tissues. "Analysis of 19,000 cancer samples from The Cancer Genome Atlas (TCGA) and International Cancer Genome Consortium (ICGC) revealed mutations in RPL5 and RPL11 in 139 and 74 cases, respectively, indicating their involvement in cancer pathogenesis." (PMID 40805230, 2025). "Heterozygous RPL5 and RPL11 mutations or deletions have been identified in spontaneous human cancer." (PMID 34462428, 2021). "In addition to RPL11, our study highlights several other ribosomal proteins that have been implicated in cancer progression, such as Ribosomal Protein S4 X (RPS4X) and eukaryotic translation initiation factor 3 subunit i (eIF3i)." (PMID 39891297, 2025). "In total, 139 RPL5 mutations and 74 different cancer-associated RPL11 mutations have been detected across 49 cancer types; these genes were found to be mutated in 34% of breast cancers, 28% of melanomas, and up to 34% of multiple myelomas in a comprehensive analysis of 19,000 cancer samples." (PMID 38255260, 2024). "Collectively this suggests that loss of the tumor suppressive functions of RPL5 (uL18) or RPL11 (uL5) via inactivating mutations might predispose DBA patients to cancer development." (PMID 30862070, 2019). "While RPL22 is mutated in cancer and clearly implicated in MDM4 splicing, what is the evidence regarding RPL5 and RPL11 in cancer?" (PMID 40427096, 2025). "Consistent with the established anti-proliferative and pro-apoptotic roles in cancer, the study demonstrates that RPL11 is pathologically upregulated in renal tubular cells during AKI, and it acts as a central driver of injury progression." (PMID 40895534, 2025). "Recurrent mutations in genes of the large 60S subunit components RPL5, RPL10, RPL11, RPL22, and RPL23A, and the small 40S subunit components RPS15, RPS20, and RPS27 have been specifically implicated in cancer." (PMID 40805230, 2025). "Among the 34 RPs exhibiting an increased ratio in cancer, missense mutations in RPL11 and RPL5 occur in 73% and 66% of the 19,000 cancer samples across 49 cancer types." (PMID 39086661, 2024). "The co‐IP assays revealed that BRIX1 bound to both RPL5 and RPL11 in cancer cells when treated with Act D." (PMID 39475053, 2024). "Ribosomal protein L11 (RPL11) is a component of ribosomal 60 S large subunit with different roles in different cancers." (PMID 36869281, 2023). "RPL11 is a previously reported cancer regulator RP, known to act as a tumor suppressor in several cancers." (PMID 36869281, 2023). "The case of RPL11 is also interesting because this ribosomal protein has been shown previously to modulate the sensitivity of cancer cells to various topoisomerase inhibitors, including TPT." (PMID 36838813, 2023). "As RPL5 performed both tumor activator and tumor suppressor in types of cancer cells, it’s possible that RPL11 has similar function in cancer cell growth." (PMID 36869281, 2023). "Here, we show that miR-101-3p enhances the RPL11-induced defense mechanism against abnormal cell proliferation by targeting ubiquitin-specific peptidase 47 (USP47) in cancers." (PMID 35205710, 2022).